HIF1A (hypoxia inducible factor 1 subunit alpha)
Diseases named in the same sentence as HIF1A in open-access papers (continued):
Sharing a sentence is not in itself a finding about the gene and the disease.
glioma (continued). "In this study, VH032 induces apoptosis of glioma cells and inhibits the metastatic activity of glioma cells by influencing the protein content of the VHL/HIF-1α/VEGF pathway." (PMID 41030787, 2025). "Glioma cells in the NC group were slightly enlarged in size under light microscopy compared with the sham group, while glioma cells in the HIF-1α group were significantly swollen and expanded with many bubble-like protrusions compared with the NC group." (PMID 38734702, 2024). "Apigenin can also improve the sensitivity of glioma cells to radiotherapy, thus playing somewhat an adjuvant role chiefly through repairing DNA damage in a HIF1α-mediated manner." (PMID 39407193, 2024). "HULC promotes glycolysis and the stemness of GSCs by regulating the FOXM1/AGR2/HIF-1α axis, consequently exacerbating the occurrence and development of glioma." (PMID 39272133, 2024). "The hypoxic microenvironment in gliomas activates the HIF-1α/LAMC1 signaling, thereby promoting tumor progression." (PMID 38678297, 2024). "This in turn induces angiogenesis that is associated with expression of hypoxia-inducible factor (HIF)-1α and vascular endothelial growth factor (VEGF) in perinecrotic pseudopalisading glioma cells." (PMID 38960965, 2024). "In a hypoxic microenvironment, the HIF1α/HIF2α-Sox2 network induced the formation of GSCs by dedifferentiating differentiated glioma cells, thereby promoting chemoresistance of the glioma cells." (PMID 38794149, 2024). "FGFR1 signaling also promotes radioresistance in glioma cell lines through PLCγ1 and hypoxia-inducible factor 1-alpha (HIF1α)." (PMID 38255923, 2024). "Previous studies revealed that targeting the HIF-1α/PD-L1 pathway with PD-L1 antibodies combined with the HIF-1α inhibitor PX-478 improved the efficacy of anti-PD-1/PD-L1 for glioma." (PMID 38612546, 2024). "HIF1α levels were decreased in glioma patients with high miR-448 levels but increased in patients with lower miR-448 expression; these differences were correlated with patient survival." (PMID 38786726, 2024). "The researchers investigated the reciprocal action between hypoxia, the PI3K/AKT/HIF-1α pathway, and ferroptosis in glioma cells." (PMID 38562143, 2024). "Previous studies have found that borneol promotes cellular autophagy via the mTORC1/eIF4E/HIF-1α axis, thereby sensitizing glioma cells to radiation." (PMID 38188151, 2024). "Mechanistically, the CLOCK-induced upregulation of OLFML3 enhanced LGMN transcription by modulating HIF1α in glioma stem cells." (PMID 38607733, 2024). "Through the clinical data validation of glioma patients in the CGGA database, it was also confirmed that the overexpression of HIF-1α gene was associated with poor long-term prognosis." (PMID 38734702, 2024). "As one of the most important hypoxia induced factors, HIF1A is closely related to the development of a variety of diseases, including glioma, and it can be used as a marker for the diagnosis and independent prognostic factor of disease." (PMID 38879468, 2024). "Multiple lncRNAs in gliomas can act as upstream regulatory factors for HIF-1α to regulate HIF-1α-induced glycolysis." (PMID 39272133, 2024). "The results of cell cloning assay showed that the HIF-1α group was able to significantly promote the clonogenic ability of cells and promote glioma cell stemness compared with the sham and NC groups." (PMID 38734702, 2024). "The increase in HIF-1α protein levels promotes the Warburg effect and tumorigenesis in glioma cells." (PMID 39272133, 2024). "Zhanget al. revealed that the overexpression of mitochondrial Clk1 impaired chemoresistance through the AMPK/mTOR/HIF-1α-mediated glycolytic pathway in glioma cells." (PMID 38634120, 2024). "In a murine glioma model, they demonstrated the antitumor effect of the HIF1α inhibitor PX-478 when combined with the anti-PD-L1 antibody." (PMID 38786726, 2024).
glioma (continued). "Apigenin increases radiosensitivity of subcutaneous gliomas in mice by inhibiting NF-κB/HIF-1α-mediated glycolysis and attenuating cell stemness and DNA damage repair." (PMID 38778409, 2024). "These mechanistic findings, along with the intimate link between METTL8 levels and the HIF1α/RTK/Akt axis in glioma patients, guided us to propose a HIF1α/Akt inhibitor combination which potently compromises GSC proliferation/self-renewal in vitro." (PMID 38744809, 2024). "We also found that HIF-1α had a positive correlation to LAMC1 expression in glioma, which led to analyzing the mechanism of HIF-1α-mediated LAMC1 expression." (PMID 38678297, 2024). "Apigenin sensitized glioma to radiotherapy by inhibiting glycolytic enzymes and the expression of NF-κB, p65, HIF1α, GLUT-1/3, and pyruvate kinase isozyme type M2 (PKM2) in human GSCs and a subcutaneous glioma model." (PMID 38786726, 2024). "Recent studies have shown that Hypoxia-inducible factor 1α (HIF-1α) can stimulate PD-L1 expression in malignant solid tumors, like non-small cell lung cancer, hepatocellular carcinoma, and glioma, which mediates tumor immune escape." (PMID 38612546, 2024). "CD133 upregulation in hypoxic conditions has been reported in glioma, pancreatic and renal cancer in part by HIF-1α-dependent manner." (PMID 37922108, 2024). "Correlation analysis showed that HIF-1α expression in normal brain tissue and glioma was positively correlated to LAMC1 (r = 0.499, P < 0.001)." (PMID 38678297, 2024). "Both embryonic and adult NSCs show basal HIF-1α stabilization and this molecular feature is also present in the notoriously difficult to treat high-grade gliomas." (PMID 38607059, 2024). "Borneol alone can down-regulate HIF-1α and promote apoptosis, which further validates our study’s findings that borneol induces apoptosis in glioma cells by promoting autophagy to degrade HIF-1α." (PMID 38188151, 2024). "It interacts with transcription factor RP58 and affects the RP58/PHD3/HIF-1α axis to regulate glycolysis in glioma cells." (PMID 39272133, 2024). "Glioma cells cultured under hypoxic conditions show a marked increase in HIF-1α and galectin-1 levels, both of which are typically upregulated in hypoxic environments and have cytoprotective effects." (PMID 39698411, 2024). "The activity of the Linc01060/MZF1/c-Myc/HIF1α axis was higher in human GBM biopsy samples than biopsies from low-grade glioma patients, correlating with tumor grade and a poorer clinical prognosis." (PMID 38786726, 2024). "In U87 and U259 glioma cells, the inhibition of HIF1α by PX-478 reduced the levels of procollagen-lysin 2-oxoglutarate 5-dioxygenase 2 (PLOD2), a hypoxia-induced enzyme that promotes invasion and migration in GB cells." (PMID 38786726, 2024). "However, the mechanism underlying the effect of HIF-1α in gliomas remains largely unknown." (PMID 38734702, 2024). "Two main molecules manifesting in the response to hypoxia in glioma are hypoxia-inducible factor-1α (HIF1α) and hypoxia-inducible factor-2α (HIF2α)." (PMID 38672638, 2024). "Knockdown of HIF-1α reduced migration in vitro and invasion in vivo as well as the ability of murine glioma cells to form tumor spheres." (PMID 39055895, 2024). "Secondly, hypoxia can also induce genetic changes via HIF-1α in glioma cells, leading to the activation of genes involved in tumor growth, invasion, and resistance to therapy." (PMID 38654280, 2024). "2-HG stimulates PHD activity, leading to HIF1α degradation, which can prevent the glycolytic switch and decrease the elevated rate of cell proliferation typical of high-grade gliomas." (PMID 38786726, 2024). "A dysfunctional and impaired vasculature in gliomas reduces blood and oxygen supply, decreasing D* values, while HIF-1α expression increases as tumor cells grow." (PMID 39906347, 2024). "Studies have shown that HIF-1α is overexpressed in gliomas and positively correlated with the degree of malignancy." (PMID 38734702, 2024).
glioma (continued). "This study found that overexpression of HIF-1α promotes the expression of cell pyroptosis-related proteins in glioma cells." (PMID 38734702, 2024). "The colony formation assays, transwell assays, and wound-healing assays showed that overexpression of HIF-1α promoted proliferation and invasion of glioma cells." (PMID 38734702, 2024). "Based on clinical glioma tissue, we detected that the expression level of HIF-1α protein increases with the increase of pathological grade." (PMID 38678297, 2024). "The outcome of HIF1α/HIF2α-Sox2 signaling in a hypoxic microenvironment is the dedifferentiation of differentiated glioma cells leading to the formation of glioma stem cells." (PMID 38672638, 2024). "Hypoxia and the hypoxia-inducible factor (HIF)-1α promote tumor progression in gliomas by inducing anaerobic glycolysis." (PMID 39272133, 2024). "FGFR1 signaling promotes radioresistance in glioma cell lines through PLC1γ (Phospholipase C Gamma 1) and HIF1α pathways." (PMID 38255923, 2024). "On the other hand, Oct4 is induced by HIF-2α, while both HIF-2α and HIF-1α are required for the induction of VEGF expression in glioma stem cells." (PMID 39055895, 2024). "Compared with that in the untreated-tumor bearing group, the level of HIF-1α expression in animal glioma tissues treated with borneol and/or TMZ was significantly reduced, and the effect of combined therapy was even greater." (PMID 38188151, 2024). "For example, lncRNA H19 can act as a ceRNA through the miR-138/HIF-1α axis to promote the proliferation and invasion of glioma cells." (PMID 38730506, 2024). "This study found that when glioma cells overexpressed the HIF-1α gene, the cell’s proliferation and invasion abilities significantly increased, as well as the cell’s stemness." (PMID 38734702, 2024). "They collected data from the Chinese Glioma Genome Atlas (CGGA) database on 692 patients and investigated the association between HIF-1α and T-cell exhaustion-related genes and immune cells." (PMID 39202223, 2024). "On one hand, IDH1mut generation of D-2-HG can trigger gliomagenesis by interfering with DNA/histone methylation, HIF1α, and DNA damage repair, while on the other acting as a growth suppressor of established gliomas, via mechanisms such as FTO inhibition." (PMID 38445960, 2024). "Studies performed in U251MG and U87MG glioma cell lines revealed that TRPC6 influenced the stability of HIF-1α by controlling its hydroxylation." (PMID 36768856, 2023). "From this, it was evident that our triple-drug combination significantly reduced glioma proliferation by inhibiting the Nrf2/HIF-1α-mediated PI3K/GSK3β signalling pathway." (PMID 37025487, 2023). "In current study HIF1α was found to be upregulated in glioma as compared to the controls supporting the previous results." (PMID 36809279, 2023). "At the molecular level, in addition to the well-established mechanism relying on the O2-deprivation-dependent induction of HIF1α, it has been recently established that, upstream of HIF1α, lncRNA H19 regulates glioma angiogenesis." (PMID 36835628, 2023). "Remarkably, T cell exhaustion was also found to correlate with hypoxia in glioma, and both the number of exhausted T cells and the associated exhaustion markers (PD-L1, FOXO1, and PRDM1) correlated with HIF1α levels." (PMID 38239396, 2023). "We also found HIF-1α induced in hypoxia cultured glioma cells, and the expressions of LDHA and BCAT1 were also increased." (PMID 37298317, 2023). "The activity of the OR7E156P/miR-143/HIF-1α axis modulated glioma cell invasion through ZEB1 and HUVEC tube formation." (PMID 37239035, 2023). "To understand the effect of HIF-1α in glioma, we constructed glioma cell U87MG with low expression of HIF-1α." (PMID 36334237, 2023). "The transcription factor hypoxia-inducible factor 1α (HIF-1α) drives metabolic reprogramming in gliomas (GLs) under hypoxic conditions, promoting glycolysis for tumor development." (PMID 38067241, 2023).
glioma (continued). "Acting as a sponge for mir138, which targets HIF1α, lncRNA H19 promotes glioma angiogenesis in a HIF1α- and vascular endothelial growth factor (VEGF)-dependent manner." (PMID 36835628, 2023). "And the role of LINC02774 in regulating the stability of HIF‐1α and its impact on glioma progression was explored." (PMID 37701531, 2023). "Compared to low-grade gliomas, these tumor-derived endothelial cells have different angiogenic mediators, such as hypoxic inducible factor 1 alpha (HIF-1α), neural cell adhesion molecule, FGF, and angiopoietin receptor Tie-2." (PMID 37107298, 2023). "In conclusion, we identify seven ferroptosis-associated genes (SLC39A14, WWTR1, STEAP3, NOTCH2, IREB2, HIF1A, and FANCD2) in gliomas, all of which are highly expressed." (PMID 37978473, 2023). "Correspondingly, inhibition of BMAL1 in vitro using primary glioma cells results in decreased expression of HIF-1α and VEGF." (PMID 38173841, 2023). "Another study has revealed that in both GBM and lower-grade gliomas undergoing hypoxia (higher expression of HIF-1α,) the expression of FOXO1 is also elevated." (PMID 37821870, 2023). "This study investigated the anti-glycolytic effects of evofosfamide (EVO) on three canine glioma (GL)-derived cell lines with activated hypoxia-inducible factor 1α (HIF-1α)." (PMID 38067241, 2023). "Subsequently, ROC curve analysis suggested that the AUC values of WWTR1, STEAP3, SLC39A14, NOTCH2, IREB2, HIF1A, and FANCD2 were all 1.000, indicating their potential as diagnostic biomarkers for gliomas." (PMID 37978473, 2023). "Overall, HIF-1α stabilization in glioma cells induces hypoxic alterations in the peritumoral environment which lead to a pro-convulsive state." (PMID 38026690, 2023). "In subsequent validation experiments, overexpression of LINC02774 in U251 glioma cells significantly decreased the protein levels of HIF‐1α." (PMID 37701531, 2023). "Both sets of data revealed that HIF1A was significantly upregulated in high-grade glioma (HGG, including WHO grade III and grade IV, referred to as GBM) compared with low-grade glioma (LGG, including WHO grade I and II)." (PMID 37988165, 2023). "While hypoxia usually activates HIF-1α, in gliomas, HIF-1α stabilizes even before hypoxia occurs in the tumor or surrounding cells, indicating its independence from hypoxia." (PMID 38026690, 2023). "Xing-Chen Ding proved that targeting HIF1α can improve the therapeutic effect of anti-PD-1/PD-L1 in glioma." (PMID 37790761, 2023). "Hypoxia and highly expressed HIF-1α is one of the main characteristics of glioma, especially glioblastoma." (PMID 37234776, 2023). "TCGA database analysis showed that SOX9 is positively related to Hif1α, a hypoxia-related protein, in glioma." (PMID 36810326, 2023). "LncRNA H19 promotes angiogenesis in gliomas by increasing the expressions of hypoxia inducible factor 1 subunit alpha (HIF-1α) and vascular endothelial growth factor (VEGF) through targeting miR-138." (PMID 36819921, 2023). "In the same study, combination treatment with a HIF-1α inhibitor and anti-PD-L1 antibody in a glioma murine model inhibited tumor growth more profoundly as compared to either monotherapy." (PMID 37958373, 2023). "Brain CSCs are more resistant under hypoxic conditions, and the depletion of HIF-1α influences the proliferation of glioma-derived brain CSCs by blocking the interaction of HIF-1α and NICD." (PMID 38201528, 2023). "RT-PCR was used to analyze the significantly reduced expression of NCX2 and HIF-1α in glioma cell lines." (PMID 36334237, 2023). "In this study, we found that GA-MSCs upregulated CD73 expression on MDSCs via exosomal miR-21 through the PTEN/PI3K/AKT/HIF-1α pathway, promoting the formation of an immunosuppressive microenvironment and the progression of glioma." (PMID 37481646, 2023).
glioma (continued). "Meanwhile, glioma cell U87MG with a low expression of HIF-1α was constructed, and its invasion and migration ability in a hypoxic microenvironment was detected." (PMID 36334237, 2023). "In glioma cells, the direct binding between HIF-1α and CD274 promoter region results in elevated PD-L1 expression under hypoxia." (PMID 36747292, 2023). "By using the CGGA database, we found that almost all kinds of glioma pathologies highly expressed HIF1α and HIF2α." (PMID 34976166, 2022). "In contrast, weak expression of MGMT indicates MGMT promoter is highly methylated, and weak expression of HIF-1α means low hypoxia in the GSC gliomas." (PMID 36591483, 2022). "In the present study, we found that the expression of HIF-1α in glioma U251 cells was significantly up-regulated under hypoxia." (PMID 35919821, 2022). "The results of this study suggest that the high expression of Sept9 in gliomas is highly correlated with Hif-1α." (PMID 35096204, 2022). "Tumor hypoxia is a hallmark of malignant gliomas, and it has been demonstrated in vivo and in vitro that glioma cells overexpress HIF-1α, which results in the activation of VEGF or MMPs." (PMID 35454935, 2022). "In conclusion, hypoxia enhanced glioma resistance to SAS-induced ferroptosis by upregulating SLC7A11 via activating the PI3K/AKT/HIF-1α axis." (PMID 36439690, 2022). "In gliomas, the hypoxia-inducible factor 1-alpha (HIF-1a) is a significant pro-angiogenic and pro-glycolysis transcription factor that is increased in IDH1 mutant GB cells." (PMID 35806212, 2022). "CA promotes apoptosis while inhibiting the proliferation of glioma cells, but is it related to Hif-1α and Sept9?" (PMID 35096204, 2022). "We utilized the C11-BODIPY probe and observed that the HIF-1α inhibitor, PX-478 (20 μM), significantly increased lipid peroxidation levels in glioma cells." (PMID 36439690, 2022). "In our study, it was found that HIF1α of glioma cells under hypoxia treatment entered the nucleus and the expression increased significantly, and the changes of AKT, mTOR, and ERK1/2 under silvestrol treatment were rescued." (PMID 35677890, 2022). "To date, no research has been performed on evaluating the usage of IVIM and R2* Mapping to visualize HIF-1α expression in glioma." (PMID 35785202, 2022). "The PI3K/AKT pathway was reported to be the upstream of HIF-1α, which had been reported to participate in the malignant progression of glioma and was considered as an important regulator of ferroptosis." (PMID 36439690, 2022). "Our observation of lower tissue acidity in IDH mutant gliomas supports previous reports of decreased levels of hypoxia-inducible factor 1 alpha (HIF1α) and HIF1α-responsive genes, including essential genes involved in glycolytic process." (PMID 35626127, 2022). "We addressed this question and performed a series of studies to verify that both HIF1α and HIF2α regulate glioma cell dedifferentiation in a hypoxic microenvironment through Sox2." (PMID 34976166, 2022). "We then analyzed the public data and found that the expression of SLC7A11 was positively correlated with HIF-1α in 257 glioma tumor samples." (PMID 36439690, 2022). "Studies have demonstrated that the molecules involved in the response to hypoxia in glioma are mainly hypoxia-inducible factor-1α (HIF1α) and hypoxia-inducible factor-2α (HIF2α), which lead to chemoresistance by maintaining GSC stemness." (PMID 34976166, 2022). "The stiff matrix promotes HIF1A expression in glioma cells and, as a result, increases tenascin C expression, which is critical for glioma aggression." (PMID 35205794, 2022). "ARRB2 plays a negative regulatory role in glioma growth, invasion, and metastasis by reducing HIF-1α expression and inhibiting angiogenesis." (PMID 36284630, 2022). "In contrast to the emerging knowledge in gliomas and leukemias, little is known regarding the effect of IDH mutation or D-2HG on HIF-1α activity in chondrosarcoma." (PMID 35198082, 2022).